CHRNE (cholinergic receptor nicotinic epsilon subunit)
Description:
After binding acetylcholine, the AChR responds by an extensive change in conformation that affects all subunits and leads to opening of an ion-conducting channel across the plasma membrane.
Synonyms: ACHRE; CMS1A1; CMS1D; CMS1E; CMS2A; CMS4A; CMS4B; CMS4C; FCCMS; FIM1; FIMG; FIMG1; MGI; SCCMS
Tractability: Small molecule: an approved drug acts on it; a high-quality ligand is known; it belongs to a druggable protein family. Antibody: its Gene Ontology location is reachable by antibodies, with high confidence; UniProt places it where antibodies can reach, with medium confidence; UniProt predicts a signal peptide or a membrane-spanning region. PROTAC: a small molecule that binds it is known.
Target class: Ion channel; Nicotinic acetylcholine receptor epsilon subunit; Nicotinic acetylcholine receptor; Ligand-gated ion channel
Gene: Protein-coding gene on chromosome 17 (4,897,771 to 4,934,438, reverse strand). Ensembl gene ENSG00000108556.
Subcellular location: Postsynaptic cell membrane; Cell membrane
Pathways (Reactome):
Neuronal System: Highly sodium permeable postsynaptic acetylcholine nicotinic receptors
Gene Ontology:
Molecular function: transmitter-gated monoatomic ion channel activity involved in regulation of postsynaptic membrane potential; acetylcholine receptor activity; acetylcholine-gated monoatomic cation-selective channel activity; monoatomic cation transmembrane transporter activity; extracellular ligand-gated monoatomic ion channel activity; monoatomic ion channel activity; neurotransmitter receptor activity; transmembrane signaling receptor activity
Biological process: acetylcholine receptor signaling pathway; calcium ion transport; membrane depolarization; monoatomic ion transmembrane transport; muscle contraction; signal transduction; skeletal muscle contraction; synaptic transmission, cholinergic; cell communication; chemical synaptic transmission, postsynaptic; excitatory postsynaptic potential; monoatomic cation transmembrane transport; monoatomic ion transport; regulation of membrane potential; regulation of postsynaptic membrane potential; signaling
Cellular component: acetylcholine-gated channel complex; neuromuscular junction; neuron projection; plasma membrane; synapse; membrane; postsynaptic membrane
Genetic constraint (gnomAD): Loss-of-function variants: 60 observed, 57.31 expected, observed/expected ratio (o/e) 1.05, 90% interval 0.85 to 1.3. The synonymous counts are far from expectation, so gnomAD's model fits this gene poorly and the ratio says little. Missense variants: 793 observed, 688.8 expected, observed/expected ratio (o/e) 1.15, 90% interval 1.09 to 1.22. Synonymous variants: 385 observed, 296.28 expected, observed/expected ratio (o/e) 1.3, 90% interval 1.2 to 1.41.
Homologues: Orthologues: chimpanzee CHRNE (99% identical), macaque CHRNE (96% identical), pig CHRNE (88% identical), mouse Chrne (88% identical), rat Chrne (87% identical), rabbit CHRNE (86% identical), guinea pig CHRNE (85% identical), dog CHRNE (75% identical), zebrafish chrne (55% identical), tropical clawed frog chrne (54% identical). Paralogues in human: CHRNG (52% identical), CHRND (46% identical), CHRNB1 (38% identical), CHRNB2 (35% identical), CHRNA2 (34% identical), CHRNB4 (34% identical), CHRNA3 (33% identical), CHRNA6 (33% identical), CHRNA4 (33% identical), CHRNA1 (29% identical), CHRNA5 (29% identical), CHRNB3 (29% identical), and 33 more.
Diseases named in the same sentence as CHRNE in open-access papers:
CHRNE is named in the same sentence as 32 diseases in open-access papers, as found by Europe PMC text mining. Sharing a sentence is not in itself a finding about the gene and the disease. The quoted sentences say what the papers report.
congenital myasthenic syndrome (12 papers, 2012 to 2025). Congenital myasthenic syndrome (CMS) is a group of genetic disorders of impaired neuromuscular transmission at the motor endplate characterized by fatigable muscle weakness. "Cholinergic receptor nicotinic epsilon (CHRNE) subunit mutations cause postsynaptic type of congenital myasthenic syndrome either as a primary acetylcholine-receptor deficiency or abnormal channel kinetics in the receptor." (PMID 38034490, 2023). "CHRNE is one of the most common genes responsible for congenital myasthenic syndromes, and mutations can lead to muscle hypotonia, weakness or developmental delays." (PMID 36981086, 2023). "The epsilon subunit of acetylcholine receptor, CHRNE, is a transmembrane protein and mutations in CHRNE have been associated with congenital myasthenic syndrome which is characterized by compromised neuromuscular transmission and muscle weakness." (PMID 32903789, 2020). "CHRNE is a transmembrane acetylcholine receptor (AChR) and its mutations lead to congenital myasthenic syndrome which is responsible for perturbation on calcium signaling and post-synaptic Ca2+ accumulation." (PMID 32903789, 2020). "An isolated ATP synthase deficiency due to the pathogenic variant 317-2A>G in the TMEM70 gene and congenital myasthenic syndrome due to the deletion of 1267delG in the CHRNE gene was referred to later." (PMID 29678161, 2018). "For congenital myasthenic syndrome, patients originating from four North African countries and living in France share the same haplotype bearing the c.1293insG mutation affecting the CHRNE gene." (PMID 22908982, 2012). "Congenital myasthenic syndrome-4C (CMS4C) associated with acetylcholine receptor (AChR) deficiency is an autosomal recessive defect of the motor endplate caused by homozygous or compound heterozygous mutations in the CHRNE gene on chromosome 17p13." (PMID 39941166, 2025). "Background and Clinical Significance: Congenital myasthenic syndrome-4C (CMS4C) associated with acetylcholine receptor (AChR) deficiency is an autosomal recessive defect of the motor endplate caused by homozygous or compound heterozygous mutations in the CHRNE gene on chromosome 17p13." (PMID 39941166, 2025). "For instance, congenital myasthenic syndrome patients living in France and originating from Tunisia, Algeria, Morocco, and Libya share the same haplotype associated with the point founder mutation (c.1293insG) in CHRNE which has been also found in patients from the Maghreb." (PMID 33679882, 2021).
Alzheimer disease (3 papers, 2015 to 2025). A progressive, neurodegenerative disease characterized by loss of function and death of nerve cells in several areas of the brain leading to loss of cognitive function such as memory and language. "We dissect distributional regulatory effects at established Alzheimer’s Disease (AD) risk genes including PITRM1, TMEM106B, and the CHRNE/SCIMP/RABEP1 cluster, revealing complex context-dependent regulatory architecture missed by linear analysis." (PMID 41377971, 2025). "Here, we add six variants associated with Alzheimer’s disease risk (near APP, CHRNE, PRKD3/NDUFAF7, PLCG2 and two exonic variants in the SHARPIN gene)." (PMID 34099642, 2021). "At Alzheimer’s disease (AD) risk loci, qQTL analysis revealed complex regulatory architecture including variance effects at PITRM1, lower-quantile-specific effects at TMEM106B partially explained by APOE ε4 interactions, and coordinated epigenetic regulation at loci harboring CHRNE/SCIMP/RABEP1." (PMID 41377971, 2025). "Among the analysed target genes, nicotinic acetylcholine receptors (CHRNB3, CHRNE, CHRNB1, CHRND) were found, which are targets of drugs against Alzheimer's disease." (PMID 26693857, 2015).
adenomyosis (1 paper, 2025). The growth of endometrial tissue inside the muscular wall of the uterine corpus. "Through bioinformatics analysis, this study identified three key genes closely associated with adenomyosis: LIPH, CYP2E1, and CHRNE." (PMID 40832467, 2025). "To thoroughly investigate potential associations between immune cell infiltration and diagnostic biomarkers in adenomyosis, we systematically analyzed the correlations between 28 immune cell types and three diagnostic markers (LIPH, CYP2E1, and CHRNE)." (PMID 40832467, 2025).
liver cancer (1 paper, 2022). An epithelial or non-epithelial malignant neoplasm that arises from the liver. "CHRNE, GFRA2, GFRA3, and GRIN2D may serve as potential biomarker for liver cancer prognosis or immune response." (PMID 35646712, 2022).
myasthenia (1 paper, 2026). "Although most of the patients with mutations in established CMS genes (such as DOK7, MUSK, RAPSYN, CHRNA1, CHRNB1, CHRND, and CHRNE) do not show cognitive symptoms, in some newly identified CMS subtypes, myasthenia is only one element of a more severe and complex clinical spectrum." (PMID 41575592, 2026).
optic atrophy (1 paper, 2012). A disorder characterized by loss of optic nerve fibers. "The age of the founder event was estimated to approximately 700 years for c.1293insG mutation in CHRNE gene, 80 generations for the autosomal non syndromic optic atrophy (2400 years) and calculated to have arisen in the second half of the 13th century for Creutzefeldt-Jacob disease." (PMID 22908982, 2012).
schizophrenia (1 paper, 2022). A major psychotic disorder characterized by abnormalities in the perception or expression of reality. "In a similar fashion but involving even longer-range RIs (~700-1000kb), we implicated a second gene encoding an acetylcholine receptor subunit, CHRNE, in schizophrenia." (PMID 35316269, 2022). "For instance, using brain regulatory-interactions for augmentation, we were able to implicate two acetylcholine receptor subunits involved in post-synaptic chemical transmission, namely CHRNB2 and CHRNE, in schizophrenia." (PMID 35316269, 2022).
scoliosis (1 paper, 2024). A congenital or acquired spinal deformity characterized by lateral curvature of the spine. "Finally, scoliosis itself is typically associated with mutations of the COLQ, VAMP1, and CHRNE (slow channel syndrome) genes rather than GFPT1 mutations." (PMID 39559672, 2024).
cancer (1 paper, 2022). A tumor composed of atypical neoplastic, often pleomorphic cells that invade other tissues. "Our analysis showed that CHRNE was related to cancer-associated signaling pathways, including PI3K-Akt signaling pathways and liver metabolic pathways." (PMID 35646712, 2022). "Mutations in CHRNE were reported to be associated with the myasthenic syndrome; however, it was never associated with cancer." (PMID 35646712, 2022).
tumor (1 paper, 2019). "CHRNA5, CHRNA10, CHRNB4, CHRND, CHRNE, and CHRNG, however, were not expressed at levels significantly different from the non-tumor control samples." (PMID 31590360, 2019).
CHRNE also shares sentences with these, for which no sentence is quoted: mastitis (4 papers); epilepsy (2); albinism (1); brain malformations (1); channelopathies (1); chronic sinusitis (1); congenital myopathy (1); dementia (1); developmental delays (1); diabetes (1); hearing loss (1); infection (1); Intellectual disability (1); Lambert-Eaton myasthenic syndrome (1); muscular dystrophies (1); myopathy (1); neurodevelopmental disorder (1); neurofibromatosis (1); neurological disease (1); of arthrogryposis (1); ophthalmoplegia (1); Spastic paraplegia (1).